ZEB1 (zinc finger E-box binding homeobox 1)
Diseases named in the same sentence as ZEB1 in open-access papers (continued):
Sharing a sentence is not in itself a finding about the gene and the disease.
breast carcinoma (continued). "The results revealed that MEK1 inhibitor treatment combined with irradiation could decrease the migratory potential of breast cancer cells including reduction of miR-221 and corresponding downstream ZEB1 (EMT) marker expression." (PMID 33327491, 2020). "Moreover, we found a strong positive correlation between the expression of p-RB (an indicator of CDK4/6 activity), p-USP51 and ZEB1 in metastatic human breast cancer samples." (PMID 32296027, 2020). "Given that the EMT-inducing transcription factor ZEB1 plays an essential role in cancer cell plasticity and tumor recurrence, future studies should focus on the role CDK4/6-USP51 signaling plays in breast cancer initiation, aggressiveness and therapy resistance through ZEB1." (PMID 32296027, 2020). "Knockdown of ZEB1 in breast cancer, non-small cell lung carcinoma, and osteosarcoma cell lines leads to an increase in the sensitivity to radiotherapy while its ectopic expression in cell models of breast cancer decreases the sensitivity." (PMID 33114182, 2020). "Conversely, mesenchymal-epithelial transition (MET) process was occurred with decreased ZEB1 level, when metastatic breast cancer was formed in a distant location, to recover the epithelial features and lose the mesenchymal/motile phenotype with a low ZEB1 level." (PMID 32014049, 2020). "Likewise, knockdown of ZEB1, an EMT transcription factor, in human breast cancer cells reduced β-tubulin isotype classes I, III, and IVB mRNA, whereas upregulation of ZEB1 was associated with increases in these isotype classes." (PMID 35582143, 2019). "Having uncovered a significant association between stromal ZEB1 and disease progression in breast cancer patients, we used the MMTV-PyMT breast cancer mouse model as a means to directly dissect the roles for stromal versus epithelial ZEB1 in mammary tumour progression in vivo." (PMID 31324807, 2019). "We next evaluated whether ZEB1 deletion in stromal fibroblasts could affect their crosstalk with the PyMT-induced breast cancer cells, which in turn impairs their abilities to promote the in vitro migration and invasion of cancer cells." (PMID 31324807, 2019). "The analysis of breast cancer cell lines panels with different degrees of aggressiveness, together with the evaluation of a battery of kinase inhibitors, allowed us to expose a robust correlation between ZEB1 and PKCα both at mRNA and protein levels." (PMID 31828042, 2019). "Indeed, a positive correlation between ZEB1 and PKCα expression levels was found for the different breast cancer cell lines used in this analysis (r = 0.82, p < 0.001)." (PMID 31828042, 2019). "Nevertheless, our findings suggest that tumour stroma-derived ZEB1 might be implied as a potential prognostic marker for breast cancer, and may be other cancer types." (PMID 31324807, 2019). "Collectively, these data suggest that ZEB1 is predominantly expressed in breast tumour stroma, and increased expression of stromal ZEB1 worsens overall survival and relapse-free survival rates in breast cancer patients." (PMID 31324807, 2019). "The human breast cancer tissues were thus stained with anti–E-cad and anti-ZEB1 antibodies." (PMID 31331982, 2019). "Bioinformatic analysis of a public human breast cancer data set (GSE9014) of stromal gene expression revealed that ZEB1 expression levels in the tumour stroma were significantly higher than in the normal stroma, and were markedly increased upon tumour progression." (PMID 31324807, 2019). "The high CAM6/CAM5/E-cad and E-cad/ZEB1 mRNA expressions were significantly associated with poorer relapse-free survival in the Her2+ER−PR−, but not in the Her2−ER+PR+ and Her2−ER−PR−, breast cancer patient cohorts." (PMID 31331982, 2019).
breast carcinoma (continued). "PD-L1 expression in EMT-activated breast cancer cells depends on the EMT-TF (ZEB1)." (PMID 31075939, 2019). "Previous study has revealed that miR-101 could directly target ZEB1 to repress ZEB1 expression at post-transcriptional level in breast cancer." (PMID 31092700, 2019). "Interestingly, stroma-corrected ZEB1 expression showed a strong and reproducible inverse relationship with immune cell abundance, particularly in breast cancer samples." (PMID 31780722, 2019). "Despite aberrant ZEB1 expression in various kinds of human cancers, including breast cancer, it was also recognized that this protein might play a pivotal role in therapeutic resistance." (PMID 30976202, 2019). "To further determine the expression pattern of ZEB1 in mouse breast cancer, we performed immunostaining of mammary tumours from MMTV-PyMT, MMTV-ErbB2/neu and MMTV-Wnt1 transgenic mice, which spontaneously develop luminal B, HER2+ and basal subtype of breast cancer, respectively." (PMID 31324807, 2019). "Additionally, RUNX1 suppress the growth of several breast cancer cell lines through the repression of cancer stem cell activity and inhibition of zinc finger E-Box binding protein 1 (ZEB1) expression." (PMID 31592165, 2019). "Moreover, ZEB1 expression was still a strong indicator of poor survival in breast cancer patients in our study." (PMID 30976202, 2019). "Therefore, we propose that ZEB1 deletion in stromal fibroblasts reduces the secretion of these pro-tumourigenic signalling molecules to the surrounding stroma, thus suppressing mammary tumour growth and progression in a paracrine fashion." (PMID 31324807, 2019). "Moreover, either Masson’s trichrome staining or immunofluorescent staining of mammary tumour sections indicated significantly reduced deposition of intratumoural type I collagen in the ZEB1-deleted stroma." (PMID 31324807, 2019). "Because the deposition of ECM and the recruitment of immune cells as well as endothelial cells are critical steps during tumour progression, we assessed the impact of ablation of stromal fibroblast-derived ZEB1 on the growth and invasion of mammary tumour epithelial cells in vivo and in vitro." (PMID 31324807, 2019). "From these experiments, we conclude that ZEB1 ablation in stromal fibroblasts results in impaired ECM deposition and reduced recruitment of cancer-associated immune cells and endothelial cells within mammary tumours." (PMID 31324807, 2019). "Likewise, miR-340 and Zeb1 display a feed-forward loop involved in breast cancer progression, and miR-145 and Zeb2 leading to prostate cancer." (PMID 29843425, 2018). "Collectively, these data demonstrate that ZEB1 can reduce breast cancer chemosensitivity in vivo." (PMID 29352223, 2018). "Next, we determined whether elevated ZEB1 expression in breast cancer cells influences tumor response to chemotherapeutic treatment in vivo." (PMID 29352223, 2018). "Therefore, our study reveals the possibility that ZEB1 acts as a determinant of chemoresistance in breast cancer." (PMID 29352223, 2018). "Mechanistically, ZEB1 has been shown to bind promoters of epithelial polarity genes including Crumb3, HGL2, and PATJ (Pals1-associated tight junction), resulting in their repression and the invasive shift in breast cancer cells." (PMID 32309604, 2018). "For example, ZEB1 facilitates bone‐specific metastasis of breast carcinomas by inducing expression of noggin, follistatin and chordin‐like 1, extracellular antagonists that inactivate ligands of the activin, and bone morphogenetic protein branches of the TGFβ family." (PMID 29744893, 2018). "However, to confirm that changes in Vimentin and E-cadherin expression were via direct regulation by ZEB2 and not by direct interactions with FOXP3 or miR-155, we then depleted the breast cancer cells of ZEB1 or ZEB2 using siRNAs." (PMID 29963231, 2018).
breast carcinoma (continued). "Finally, downregulation of ZEB1 increases the sensitivity of breast cancer cells to chemotherapy in vitro and in vivo." (PMID 29352223, 2018). "ZEB1 expression positively correlates with breast cancer aggressiveness and metastatic potential." (PMID 29744893, 2018). "Snail1 positively regulates the expression of other EMT‐TFs, such as the ZF and homeobox transcription factor ZEB1, whose transcription is induced by a complex between Snail1 and Twist1 during breast cancer EMT in response to transforming growth factor β (TGFβ)." (PMID 29729076, 2018). "Our work reveals a key role for ZEB1 in breast cancer chemoresistance." (PMID 29352223, 2018). "We therefore conclude that TENM2 may represent a gene whose transcriptional repression by ZEB1 may reflect an adaptation of breast cancer cells to an intermediate level of malignancy." (PMID 29744893, 2018). "On the other hand, up-regulation of Zeb1 is also modulated by several microRNAs such as miR-101, miR-200 and miR-150 in colon carcinoma and indirectly by miR-200 downregulation in breast cancer." (PMID 29843425, 2018). "Furthermore, Rab2A interacts with and activates Erk1/2, resulting in increased Zeb1 expression and β-catenin nuclear accumulation, which in turn promotes breast cancer stem cells functions and tumorigenesis." (PMID 30158579, 2018). "Aberrant expression of ZEB1 has been observed in many human cancers, including breast cancer." (PMID 29510731, 2018). "One previous study found that S100A16 could promote EMT in breast cancer cells by elevating the expression of transcription factors Notch1, ZEB1, and ZEB2." (PMID 29746588, 2018). "In addition, Gene Set Enrichment Analysis (GSEA) of Zeb1 depleted breast cancer cells showed its activating role in the expression of inflammatory response genes IL-6, IL-8, and IL-1α." (PMID 30483264, 2018). "Expression of ZEB1 is increased in breast cancer and positively correlates with ATM protein levels." (PMID 29352223, 2018). "Thus, inactivation of the ZEB1 gene had significant phenotypic effects on these breast cancer cells." (PMID 29744893, 2018). "These genes provide new clues to the function of ZEB1 in breast cancer." (PMID 29744893, 2018). "Similarly, in breast cancer, a positive feedback regulation of ZEB1 and β-tubulin isotype classes I, III, and IVB has been reported." (PMID 28677634, 2017). "Moreover, ectopic expression of ZEB1 in breast cancer is readily influenced by microenvironmental signals such as TGF-β, resulting in CSCs population expansion by non-CSCs to CSCs conversion and increased tumorigenesis." (PMID 28903350, 2017). "Notably, the downregulation of ZEB1 restores ER-α activity and thus increases the sensitivity of breast cancer cells to antiestrogen treatment in vitro and in vivo." (PMID 28383555, 2017). "This study proved that epigenetic regulation of ZEB1 may be a key biomarker for predicting resistance to breast cancer therapies." (PMID 29245917, 2017). "Targeted therapies against the ZEB1/Ngn3 axis may be highly valuable for the prevention and treatment of breast cancer." (PMID 28903350, 2017). "To further confirm that the inhibition of Ngn3 expression by ZEB1 in breast cancer is correlated with DNA methylation, we conducted bisulfite sequencing PCR (BSP) to evaluate the methylation status of 13 CpG residues in the 243-bp DMR region (-164/+79) of the Ngn3 promoter." (PMID 28903350, 2017). "Results showed that co-delivery of miR-34a and TQ is able to inactivate EMT signaling pathway by directly targeting TWIST1 and ZEB1 in BT-549 cell line, indicating that they might be a promising therapeutic combination against breast cancer metastasis." (PMID 28423483, 2017). "Expression profiling revealed 780 genes for which the expression level was affected by the loss of DIP2C, including the tumour-suppressor encoding CDKN2A gene, the epithelial-mesenchymal transition (EMT) regulator-encoding ZEB1, and CD44 and CD24 that encode breast cancer stem cell markers." (PMID 28716088, 2017).
breast carcinoma (continued). "The ZEB1‐regulated inflammatory phenotype identified in this study was characterized by enhanced breast cancer cell growth, fibroblast proliferation, and PMN‐MDSC accumulation, although each of these was observed only in certain cell types and was context dependent." (PMID 28618162, 2017). "Perhaps consistent with this, breast cancers expressing higher levels of the epithelium-promoting miR-200 family that represses the CDH1-suppressing EMP drivers ZEB1 and ZEB2 have poorer outcomes; however, this appeared to be due to mechanisms additional to E-cadherin regulation." (PMID 28750639, 2017). "Finally, we show that the expression of ZEB1 is increased in samples from breast cancer patients and is inversely correlated with NGN3 protein levels." (PMID 28903350, 2017). "The ZEB1‐regulated inflammatory phenotype identified in this study provides insights into a mechanism that is critical for cancer progression and helps explain the poor prognosis of basal‐type breast cancer." (PMID 28618162, 2017). "Thus, downregulation of Ngn3 expression is at least partially involved in the mechanism by which ZEB1 promotes breast cancer cell stemness and tumor initiation and progression." (PMID 28903350, 2017). "Therefore, our findings suggest that ZEB1 is a crucial determinant of resistance to antiestrogen therapies in breast cancer." (PMID 28383555, 2017). "Our work reveals a key role for ZEB1 in antiestrogen resistance in breast cancer." (PMID 28383555, 2017). "Therefore, restoring ER-α expression by inhibiting ZEB1 provides a potential therapeutic strategy for restoring antiestrogen sensitivity in breast cancer." (PMID 28383555, 2017). "Next, we assessed whether ZEB1 downregulation in breast cancer cells would influence tumor response to antiestrogen treatment in vivo." (PMID 28383555, 2017). "In addition, measurement of the CD44+CD24− breast CSC population also demonstrated that ectopic expression of ZEB1 led to increased stemness properties in xenografted MDA-MB-231 breast cancer cells." (PMID 28903350, 2017). "In summary, these findings mechanistically link ZEB1 with increased angiogenesis in breast cancer and identify a novel mechanism by which ZEB1 may promote breast cancer progression." (PMID 26882471, 2016). "Moreover, shRNA knockdown of ZEB1 in breast cancer cells impairs tumor initiation ability, suggesting that conversion of non-CSCs into a CSC state is important for tumorigenesis." (PMID 27608848, 2016). "Epigenetic regulation of ZEB1 may serve as a critical biomarker for predicting resistance to breast cancer treatments." (PMID 26646320, 2016). "We previously reported that ZEB1 promotes breast cancer migration and invasion by inducing EMT." (PMID 26882471, 2016). "Consequently, ZEB1 expression promotes tumorigenesis and metastasis in mouse models and correlates with a poorer prognosis in human cancers, including breast carcinomas." (PMID 26882471, 2016). "Together, these results showed that miR-340 inhibits breast cancer progression by regulating ZEB1." (PMID 27036021, 2016). "A recent study also reveals a novel role of ZEB1 in promoting angiogenesis in breast cancer." (PMID 27411336, 2016). "ZEB1 was more strongly expressed in TN breast cancer than in the other cancers (p<.0001)." (PMID 26646320, 2016). "Epigenetic regulation of ZEB1 may prove valuable as a critical biomarker for predicting resistance to breast cancer therapies." (PMID 26646320, 2016). "As detected in breast cancer cell lines, molecular subtype analyses of human breast tumours revealed a high expression of ZEB1 and common ZEB1/YAP target genes in the claudin-low type, but also in a fraction of other subtypes, including Her2+, normal-like and luminal A types." (PMID 26876920, 2016). "Next, we determined whether elevated expression of ZEB1 in breast cancer cells influences tumor angiogenesis in vivo." (PMID 26882471, 2016).
breast carcinoma (continued). "First, as presented in this study, ZEB1 may induce VEGFA production by breast cancer cells through activation of the PI3K and p38 pathways." (PMID 26882471, 2016). "ZEB1 depletion resulted in an opposite effect, inhibiting the capillary tube formation of HUVECs and highlighting that ectopic expression of ZEB1 may contribute to tumor angiogenesis in breast cancer." (PMID 26882471, 2016). "Analysis of clinical data and patient material provides evidence for a particular relevance of our findings in aggressive breast cancer types, showing that a ‘common ZEB1/YAP target gene set' is a strong predictor of poor relapse free survival, therapy resistance and increased metastatic risk." (PMID 26876920, 2016). "Moreover, the miR-200 family member miR-429 was recently observed to be decreased in bone metastatic breast cancer cells compared to parental cells, supporting our finding of increased ZEB1 expression in bone metastases." (PMID 25973542, 2015). "In addition, miR-200c activation inhibits ZEB1 expression, resulting in E-cadherin induction in breast cancer cells." (PMID 26423775, 2015). "ZEB1/2-mediated transcriptional repression of E-cadherin is necessary for epithelial-to-mesenchymal transition, so the upregulation of ZEB1/2 could contribute to the invasiveness of tamoxifen-resistant breast cancer cells." (PMID 25849966, 2015). "This suggests that controlling ZEB1 expression through LPA1 activation might have a functional impact on basal breast cancer behaviors." (PMID 26098771, 2015). "We found lnc-ATB could promote trastuzumab resistance and invasion-metastasis cascade in breast cancer by competitively biding miR-200c, up-regulating ZEB1 and ZNF-217, and then inducing EMT." (PMID 25871474, 2015). "However, when performing microarray analysis in MDA-MB-231 breast cancer cells after stable shRNA mediated knockdown of ZEB1 (shZEB1), we observed many mRNAs to be downregulated relative to control (shCtrl) (column 5, ArrayExpress E-MTAB-3482)." (PMID 25973542, 2015). "This is in contrast to results of another study that suggests that the presence of ZEB1, and not the absence of ZEB1, is associated with tamoxifen resistance in breast cancer cells." (PMID 26090296, 2015). "In this study we demonstrated that in human breast tumors there was a significant positive correlation between LPAR1, ZEB1 and miR-21 and that in basal breast cancer cell lines ZEB1 regulates LPA-induced miR-21 expression through an LPA1/PI3K dependent mechanism." (PMID 26098771, 2015). "In addition, a separate report indicates that ER α and ZEB1 work in opposition to one another in controlling the expression of microRNAs in breast cancer cells." (PMID 26090296, 2015). "We found that lnc-ATB could promote trastuzumab resistance and invasion-metastasis cascade in breast cancer by competitively biding miR-200c, up-regulating ZEB1 and ZNF-217, and then inducing EMT." (PMID 25871474, 2015). "Additionally, activation of ZEB1/2 has been connected to NF-ĸB signaling in breast cancer cells, suggesting an involvement of the MAPK, NF-ĸB and AP-1 pathways in tumorigenesis through activation of EMT." (PMID 25793618, 2015). "ZEB1 (zinc-finger E-box-binding homeobox 1) is an important EMT activator in human breast cancer." (PMID 26423775, 2015). "And a recent study illustrated that CUL4A promoted H3K4me3 at the promoter of ZEB1 and then led to transcriptional upregulation of ZEB1 expression in breast cancer cells, and knockdown of ZEB1 blocked CUL4A-induced cell proliferation, EMT, tumorigenesis, and metastasis." (PMID 26460955, 2015). "In the current study, we reported that lnc-ATB, which had been reported to be activated by TGF-β, promote trastuzumab resistance and invasion-metastasis cascade in breast cancer by competitively biding miR-200c, up-regulating ZEB1 and ZNF-217, and then inducing EMT." (PMID 25871474, 2015).